WAS (WASP actin nucleation promoting factor)
Description:
Effector protein for Rho-type GTPases that regulates actin filament reorganization via its interaction with the Arp2/3 complex. Important for efficient actin polymerization. Possible regulator of lymphocyte and platelet function. Mediates actin filament reorganization and the formation of actin pedestals upon infection by pathogenic bacteria. In addition to its role in the cytoplasmic cytoskeleton, also promotes actin polymerization in the nucleus, thereby regulating gene transcription and repair of damaged DNA. Promotes homologous recombination (HR) repair in response to DNA damage by promoting nuclear actin polymerization, leading to drive motility of double-strand breaks (DSBs).
Synonyms: WASp; IMD2; WASPA; SCNX; THC; THC1
Tractability: Small molecule: a structure with a bound ligand is known. Antibody: its Gene Ontology location is reachable by antibodies, with high confidence; the Human Protein Atlas places it where antibodies can reach. PROTAC: ubiquitination databases record sites on it; its protein half-life has been measured.
Gene: Protein-coding gene on chromosome X (48,676,593 to 48,691,431, forward strand). Ensembl gene ENSG00000015285.
Subcellular location: Cytoplasm, cytoskeleton; Nucleus
Subcellular location (Human Protein Atlas): Plasma membrane; Cytosol
Pathways (Reactome):
Signal Transduction: CDC42 GTPase cycle; RAC1 GTPase cycle; RHO GTPases Activate WASPs and WAVEs; RHOJ GTPase cycle
Immune System: Generation of second messenger molecules; Regulation of actin dynamics for phagocytic cup formation
Disease: FCGR3A-mediated phagocytosis
Gene Ontology:
Molecular function: identical protein binding; phospholipase binding; protein binding; protein kinase binding; SH3 domain binding; small GTPase binding; GTPase regulator activity; actin binding
Biological process: actin filament polymerization; Cdc42 protein signal transduction; immune response; negative regulation of cell motility; negative regulation of stress fiber assembly; positive regulation of double-strand break repair via homologous recombination; positive regulation of transcription by RNA polymerase II; regulation of actin polymerization or depolymerization; regulation of double-strand break repair via nonhomologous end joining; regulation of lamellipodium assembly; regulation of stress fiber assembly; regulation of T cell antigen processing and presentation; Rho protein signal transduction; actin polymerization or depolymerization; blood coagulation; defense response; epidermis development; protein-containing complex assembly; actin filament organization
Cellular component: actin filament; cytosol; extracellular exosome; nucleus; site of double-strand break; actin cytoskeleton; cell-cell junction; cytoplasm; cytoskeleton; phagocytic vesicle; vesicle membrane
Gene-disease validity (ClinGen):
ClinGen rates the evidence that WAS causes each of these diseases.
Wiskott-Aldrich syndrome (X-linked): Definitive. Wiskott-Aldrich syndrome (WAS) is a primary immunodeficiency disease characterized by microthrombocytopenia, eczema, infections and an increased risk for autoimmune manifestations and malignancies.
X-linked severe congenital neutropenia (X-linked): Definitive. This syndrome is an immunodeficiency syndrome characterized by recurrent major bacterial infections, severe congenital neutropenia, and monocytopenia.
Cancer hallmarks: invasion and metastasis (promotes)
Homologues: Orthologues: chimpanzee WAS (99% identical), macaque WAS (98% identical), dog WAS (92% identical), pig WAS (90% identical), mouse Was (89% identical), rat Was (87% identical), guinea pig WAS (84% identical), rabbit WAS (77% identical), zebrafish wasb (50% identical), zebrafish wasa (46% identical), tropical clawed frog was (45% identical), Caenorhabditis elegans C31C9.6 (25% identical), and 2 more. Paralogues in human: WASL (51% identical).
Diseases named in the same sentence as WAS in open-access papers:
WAS is named in the same sentence as 154 diseases in open-access papers, as found by Europe PMC text mining. Sharing a sentence is not in itself a finding about the gene and the disease. The quoted sentences say what the papers report.
Wiskott-Aldrich syndrome (124 papers, 2006 to 2026). "WAS is a protein-coding gene associated with diseases such as Wiskott-Aldrich syndrome and neutropenia, which can lead to malignant tumor development." (PMID 40511304, 2025). "Named after both physicians, Wiskott-Aldrich Syndrome is caused by hemizygous alterations in the WAS gene, which was mapped to Xp11.23 in 1994 and encodes WAS protein (WASp)." (PMID 40925926, 2025). "Wiskott-Aldrich syndrome (WAS) is the first-described and best known actinopathy, which is caused by mutations in the WAS gene, causing thrombocytopaenia, eczema, recurrent infections, autoimmunity and malignancy." (PMID 40748381, 2025). "Mutations in the Wiskott-Aldrich syndrome gene, WAS, which codes for WAS protein (WASp), can lead to an eponymous X-linked immunodeficiency called Wiskott-Aldrich syndrome (WAS)." (PMID 41181176, 2025). "Wiskott-Aldrich Syndrome (WAS) is a combined syndromic inborn error of immunity (IEI) caused by loss-of-function mutations in the WAS gene, located on the X chromosome." (PMID 41035657, 2025). "Pathogenic variants in the WAS gene cause Wiskott-Aldrich syndrome, an X-linked recessive immunodeficiency disease characterized by thrombocytopenia, eczema, and recurrent infections." (PMID 37294900, 2024). "Defects in WASP are the cause of Wiskott-Aldrich syndrome (WAS), an X-linked recessive disorder characterized by immune dysregulation and micro thrombocytopenia." (PMID 37641121, 2023). "Mutations in WASP are known to cause Wiskott-Aldrich Syndrome (WAS), a complex systemic disorder combining immunodeficiency, autoimmunity, autoinflammation, atopies and predisposition to malignancy." (PMID 37382373, 2023). "He carried a likely pathogenic hemizygous nonsense variant NM_000377.3:c.889C > T (p.Gln297Ter) in the WAS gene related to Wiskott-Aldrich Syndrome (OMIM #301000)." (PMID 37592284, 2023). "The Wiskott-Aldrich syndrome (WAS) is an X-linked disorder caused by a mutation in the Wiskott-Aldrich syndrome (WAS) gene, which encodes for the Wiskott-Aldrich syndrome protein (WASP)." (PMID 36044170, 2023). "Wiskott-Aldrich syndrome, a condition marked by immunological dysregulation, can be brought on by mutations in the WAS gene." (PMID 37529244, 2023). "The diverse functions of WASP, the deficiency of which causes Wiskott-Aldrich syndrome (WAS), remain poorly defined." (PMID 35752626, 2022). "Wiskott-Aldrich syndrome (WAS), another rare X-linked congenital syndrome caused by mutations in the WAS gene and playing an important role in actin cytoskeleton remodeling specifically in HSCs, was also targeted by ZFN gene editing." (PMID 36553489, 2022). "Wiskott-Aldrich syndrome is a genetic disease, caused by WAS gene mutations and alteration of cytoskeleton of both immune cells and platelets." (PMID 35125118, 2022). "Wiskott-Aldrich syndrome (WAS) is a severe X-linked primary immunodeficiency caused by the mutations of the WAS gene on the X-chromosome." (PMID 34169073, 2021). "Wiskott-Aldrich Syndrome (WAS) occurs with a mutated WAS gene leading to a reduced or absent WAS protein expression which leads to actin filament defect in hematopoietic cells." (PMID 34122435, 2021). "In a classical example, Wiskott-Aldrich syndrome is caused by defects in the WAS protein (WASP), which plays essential roles in the regulation of the actin cytoskeleton upon cell activation." (PMID 33692789, 2021). "Sixty-four patients had a Del 22q11.2 defect (DiGeorge syndrome), 63 had an ataxia telangiectasia mutated gene (ATM) (A-T), 36 had a STAT3 mutation (Hyper IgE syndromes), 24 had a WASP mutation [Wiskott-Aldrich syndrome (WAS)]." (PMID 31379802, 2019). "The Wiskott-Aldrich syndrome (WAS) occurs in males with hemizygous mutations in the X-chromosomal WAS gene." (PMID 31750279, 2019). "Wiskott-Aldrich Syndrome (WAS) is a rare X-linked recessive Primary Immunodeficiency (PID) caused by mutations in WAS gene which encodes a protein known as WASp." (PMID 31379999, 2019).
Wiskott-Aldrich syndrome (continued). "Wiskott-Aldrich syndrome (WAS) is a recessive X-linked inmmunodeficiency caused by loss-of-function mutations in the gene encoding the WAS protein (WASp)." (PMID 30671311, 2019). "WIPF1 binds to a region of Wiskott-Aldrich syndrome protein (WASP) that is frequently mutated in Wiskott-Aldrich syndrome (WAS)." (PMID 30041660, 2018). "Wiskott-Aldrich syndrome is an X-linked recessive immunodeficiency due to mutations in Wiskott-Aldrich syndrome (WAS) gene." (PMID 30029636, 2018). "Since identification of novel mutations in WAS gene can help uncover the exact pathogenesis of Wiskott-Aldrich syndrome, the purpose of this study was to investigate disease causing-mutation in an Iranian male infant suspicious of this disorder." (PMID 30029636, 2018). "Wiskott-Aldrich syndrome (WAS) patients have loss-of-function mutations in the actin regulator WASp and suffer from immunodeficiency with increased risk to develop lymphoreticular malignancies." (PMID 27477778, 2016). "Wiskott-Aldrich syndrome is caused by mutations in the WASP-encoding WAS gene and characterized by microthrombocytopenia, eczema, recurrent infections, and autoimmunity due to dysfunctional reorganization of the actin cytoskeleton." (PMID 26345720, 2015). "In the X-linked immunodeficiency disorder Wiskott-Aldrich syndrome (WAS) the mutated WAS protein (WASP) plays the key role in impaired Treg suppressor function." (PMID 24521175, 2014). "The major focus of this review is the immune defects that result from mutations in the Wiskott-Aldrich syndrome gene (WAS), which have a broad impact on many different processes and give rise to clinically heterogeneous immunodeficiencies." (PMID 24117828, 2013). "WASP was originally discovered as the hematopoietically expressed product of the gene mutated in the X-linked immunological disorder Wiskott Aldrich Syndrome (WAS) and is an important downstream effector of Cdc42." (PMID 22505929, 2012). "WASP expression is restricted to haematopoietic cells and was discovered as the product of the gene that is mutated in the Wiskott Aldrich Syndrome (WAS), an X-linked immunological disorder diagnosed in children." (PMID 20609498, 2011). "The Wiskott-Aldrich syndrome (WAS) is a primary immunodeficiency determined by mutations in the WAS-protein (WASp), a member of a larger family of proteins (WASP family) that functions as nucleation-promoting factors for the Arp2/3 complex, which drives the generation of branched actin filaments." (PMID 35983040, 2022). "Knock-out of IFNAR in a Wiskott-Aldrich syndrome (WAS) chimera model of B cell-driven autoimmunity, where B cell-specific WAS protein deficiency results in hyperresponsive B cells, did not block development of humoral autoimmunity, nor did it prevent the generation of robust splenic GCs." (PMID 34938294, 2021). "Wiskott-Aldrich syndrome (WAS) occurs due to mutations in the WAS gene, located at Xp11.22-p11p23." (PMID 32503528, 2020). "WASL encodes a member of the Wiskott-Aldrich syndrome (WAS) protein family." (PMID 30255799, 2018). "Wiskott-Aldrich syndrome (WAS), characterised by recurrent infections and abnormal lymphocyte function is commonly caused by loss-of-function mutations in WAS protein (WASp) or in its interacting protein WIP, both of which are involved in triggering actin polymerisation downstream of Cdc42." (PMID 29337666, 2018). "Hence baby's complete gene sequencing for WAS gene was done, and it showed known pathogenic mutation c.37C>T (p.R13X) in WAS gene confirming diagnosis of Wiskott-Aldrich syndrome." (PMID 27340577, 2016). "In support of a role for the actin cytoskeleton, peripheral blood mononuclear cells (PBMCs) from Wiskott-Aldrich syndrome (WAS) patients, where mutations in the WAS protein (WASP) results in defective Cdc42-induced regulation of the actin cytoskeleton, are resistant to CD47-induced apoptosis." (PMID 23401787, 2013).
Wiskott-Aldrich syndrome (continued). "Wiskott-Aldrich syndrome (WAS) is an inborn error of immunity caused by loss-of-function mutations in the WAS gene, which encodes WASp, a key regulator of cytoskeletal remodeling." (PMID 41035657, 2025). "Wiskott-Aldrich syndrome (WAS) is a severe X-linked immunodeficiency disorder caused by mutations in the WAS gene, characterized by thrombocytopenia, eczema, and increased risk of lymphoma and autoimmunity." (PMID 40979642, 2025). "Wiskott-Aldrich syndrome (WAS), characterized by macrothrombocytopenia, eczema, autoimmunity, and lymphoid malignancies, is caused by the expression of mutated forms of the WAS gene." (PMID 38389789, 2024). "Patients with Wiskott-Aldrich syndrome (WAS) harbor mutations in the WAS gene and suffer from immunodeficiency, microthrombocytopenia, and eczema." (PMID 36044170, 2023). "Wiskott-Aldrich syndrome (WAS) is an X-linked primary immunodeficiency caused by mutations in the WAS gene that leads to increased susceptibility to infections, thrombocytopenia, eczema, malignancies, and autoimmunity." (PMID 37550789, 2023). "Wiskott-Aldrich syndrome (WAS): WAS is an X-linked disease due to a defect in the WAS gene, which manifests with thrombocytopenia, frequent infections, eczema, and increased incidence of malignancy and autoimmunity." (PMID 37111404, 2023). "WASP is mutated in Wiskott-Aldrich syndrome (WAS), which is associated with immunological deficiencies such as dermatitis, macrothrombocytopenia, and several other immune system disorders." (PMID 37126564, 2023). "A WAS gene mutation encoding the WASp causes a rare X-linked recessive disease Wiskott-Aldrich syndrome (WAS), a primary immunodeficiency with microthrombocytopenia and abnormal lymphoid and myeloid functions." (PMID 37031292, 2023). "Wiskott-Aldrich syndrome (WAS) is a rare immunodeficiency caused by mutations in WAS protein (WASp), a key hematopoietic-specific actin nucleation-promoting factor (NPF) of the WASp/WAVE family." (PMID 32721945, 2020). "Mutations have been identified in the WAS gene which cause a rare X-linked disorder called Wiskott-Aldrich syndrome (WAS)." (PMID 31275945, 2019). "The mutations on the WIPF1 binding site of WASP cause Wiskott-Aldrich syndrome (WAS) with increased susceptibility to leukemia and lymphoma." (PMID 30041660, 2018). "Our study found a novel, splice-site mutation in WAS gene and help consider the genetic counselling more precisely for families with clinical phenotypes of both Wiskott-Aldrich syndrome and inflammatory bowel disease and may suggest linked pathways between these two diseases." (PMID 30029636, 2018). "Wiskott-Aldrich syndrome (WAS) is an immune pathology associated with mutations in WAS protein (WASp) or in WASp interacting protein (WIP)." (PMID 29337666, 2018). "Wiskott-Aldrich syndrome (WAS), for example, is caused by mutations in the gene encoding the cytoskeleton protein WASP." (PMID 28744797, 2017). "Mutations in the WIPF1 binding site of WASP or in WIPF1 itself cause Wiskott-Aldrich syndrome (WAS), which predisposes people to cancer, such as leukemia and lymphoma." (PMID 27863429, 2017). "The Wiskott-Aldrich syndrome (WAS) is an X-linked primary immunodeficiency caused by mutations in the WAS gene and characterized by severe thrombocytopenia." (PMID 26502776, 2016). "Mutation in the Wiskott-Aldrich syndrome Protein (WASP) causes Wiskott-Aldrich syndrome (WAS), X-linked thrombocytopenia (XLT) and X-linked congenital neutropenia (XLN)." (PMID 25200405, 2014). "XLT is an allelic variant of Wiskott-Aldrich syndrome (WAS) and is due to mutations in the WAS gene." (PMID 21477322, 2011). "Another gene, WAS, which encodes the WASP actin nucleation-promoting factor and is a member of the Wiskott-Aldrich syndrome (WAS) family of proteins, is involved in the transduction of signals from receptors on the cell surface to the actin cytoskeleton." (PMID 40034689, 2025).
Wiskott-Aldrich syndrome (continued). "ProteinWeaver also identified two Wiskott-Aldrich Syndrome (WAS) family proteins, Wash and WASp, which were directly annotated to microtubule bundle formation." (PMID 40911650, 2025). "Wiskott-Aldrich syndrome (WAS) (MIM #301000) is a rare X-linked primary immunodeficiency due to mutations in the WAS gene, characterized by thrombocytopenia with small platelets, eczema, recurrent infections, and an increased incidence of autoimmunity and malignancies." (PMID 39917307, 2025). "Wiskott-Aldrich Syndrome (WAS) is caused by mutations in the WAS gene (Xp11.23), which encodes the WASP protein." (PMID 39712011, 2024). "Wiskott-Aldrich Syndrome (WAS) family proteins are downstream effectors of Rho family GTPases that usually function in a one-to-one correspondence to regulate branched actin nucleation." (PMID 36959278, 2023). "The Wiskott–Aldrich syndrome (WAS) protein family is involved in the transduction of signals from receptors on the cell surface to the actin cytoskeleton." (PMID 37153612, 2023). "One such family of actin nucleation factors, the Wiskott-Aldrich Syndrome (WAS) family (WASp, Scar/WAVE, WASH), works with the Arp2/3 complex to promote branched actin nucleation." (PMID 36959278, 2023). "One example is Listeria monocytogenes which facilitates interaction with the host cytoskeleton and motility of the bacterium within the host cell by mimicking Wiskott–Aldrich syndrome (WAS) family proteins." (PMID 37953771, 2023). "In WAS gene, for example, loss-of-function (LOF) mutations cause the Wiskott-Aldrich syndrome, while WAS gain-of-function (GOF) mutations lead to X-linked neutropenia with a different prognosis and therapeutic approach." (PMID 36544766, 2022). "Branched actin nucleation promoting factors include the Wiskott–Aldrich Syndrome (WAS) family of proteins: WASp, SCAR/WAVE, and WASH." (PMID 36139352, 2022). "Actin regulators include actin-monomer-binding proteins, Wiskott-Aldrich syndrome (WAS) family of proteins, nucleation proteins, actin filament polymerases and severing proteins." (PMID 35371070, 2022). "Wiskott-Aldrich syndrome (WAS) is a rare, X-linked, complex PID caused by mutations in the WAS gene which encodes the WAS protein (WASp)." (PMID 36059471, 2022). "WASL, also known as WASP, like actin nucleation promoting factor, is a member of the Wiskott–Aldrich syndrome (WAS) protein family." (PMID 34222242, 2021). "Wiskott Aldrich syndrome is an X-linked disorder associated with immunodeficiency and thrombocytopenia involving a congenital mutation in the WAS protein (WASP)." (PMID 34502272, 2021). "Wiskott-Aldrich syndrome (WAS) is caused by mutations in the X-linked WAS gene, which encodes the WAS protein (WASp)." (PMID 31519693, 2019). "WASp was the first identified member due to that its loss-of-function leads to the severe immunodeficiency disease Wiskott-Aldrich syndrome (WAS), initially described by Alfred Wiskott in 1937 and Robert Aldrich in 1954 (Wiskott A, Familiärer, angeborener Morbus Werlhofii?" (PMID 30894852, 2019). "Although rare, the presence of small platelets is consistently related to impaired expression of Wiskott-Aldrich syndrome protein (WASP), seen in both X-linked thrombocytopenia (XLT) and Wiskott-Aldrich syndrome (WAS)." (PMID 28641574, 2017). "Wiskott-Aldrich syndrome (WAS), caused by mutations in a cytoskeletal protein, WAS protein (WASp), affects dendritic cell migration and immune synapse formation with T cells but may enhance dendritic cell cross-presentation." (PMID 27755182, 2016). "Patients with Wiskott-Aldrich syndrome (WAS) lack or have reduced expression of WASp and suffer from combined immunodeficiency with recurrent infections." (PMID 25165726, 2014). "Our group has previously developed two different hematopoietic-specific LVs, WE and AWE driving the expression of eGFP through different promoter fragments of the Wiskott-Aldrich Syndrome (WAS) gene (WAS)." (PMID 22720040, 2012).